ATM (ATM serine/threonine kinase)
Diseases named in the same sentence as ATM in open-access papers (continued):
Sharing a sentence is not in itself a finding about the gene and the disease.
lung carcinoma (continued). "It has been reported that CDH1 and ATM germline mutation was associated with colorectal cancer, and MET mutation plays an important role in lung cancer and colorectal cancer development and progression." (PMID 35372080, 2022). "We showed that ubiquitin-specific protease 9X (USP9X) mediates lysine-specific demethylase 4C (KDM4C) deubiquitination, which activates transforming growth factor-β2 (TGF-β2)/Smad/ATM signaling to promote radioresistance in lung cancer." (PMID 35875060, 2022). "We identified several germline and somatic mutations (e.g., BRCA1/2, PALB2, ATM, and ATR mutations) associated with HRD phenotype in ovarian, breast, pancreatic, stomach, bladder, and lung cancer." (PMID 34572800, 2021). "For example, somatic BRCA2 and ATM mutations were correlated with HRD in bladder cancer, lung cancer, and colon cancer." (PMID 34572800, 2021). "Did ATM-regulated autophagy participate in the regulation of the sensitivity of the A549 lung cancer cells at low doses and participate in the transition from HRS to IRR?" (PMID 34055781, 2021). "The most significant GO term in the analysis, cAMP-mediated signaling, has been shown to promote radiation-induced apoptosis in human lung cancer cells via interaction with the ATM gene." (PMID 32106268, 2020). "KIAA0930 showed significant over-expression in lung cancer compared to normal lung samples in an independent dataset from Harvard18 (P = 0.0005), while ATM showed limited variability." (PMID 32393777, 2020). "For instance, in lung cancer, IL-6 regulates the expression of MMP-3 through ATM phosphorylation, a potential factor associated with drug resistance in this cancer type." (PMID 33392094, 2020). "The ATM-L2307F was found in 4.43% (MAF = 0.023) individuals from lung cancer case control study from Israel, slightly higher in North Americans (MAF = 0.002) and close to monomorphic in other European countries." (PMID 32393777, 2020). "In this study, our results showed that cisplatin-resistant lung cancer cells expressed high level ATM, and over-expressing lung cancer cells exhibited cisplatin-resistance and EMT." (PMID 30961670, 2019). "In our previous study, we found that increased ATM expression is related to cisplatin resistance formation, and knockdown ATM can enhance the sensitivity of cisplatin treatment in lung cancer cells." (PMID 30961670, 2019). "Our study sheds light on the mechanism of action of PARP inhibitors in ATM-deficient cells and reveals that the addition of an ATR inhibitor is required to induce cell death in olaparib-treated ATM-deficient lung cancer cells." (PMID 31481733, 2019). "ATM activates JAK/STAT3 signaling in cisplatin-resistant lung cancer cells, while inhibition of ATM inhibits invasion and metastasis." (PMID 31438997, 2019). "In this study, we showed that YYJD results in DNA damage, which was confirmed by the increase of ROS, γH2AX and the phosphorylation level of ATM in lung cancer cells." (PMID 28694520, 2017). "Metformin enhanced the induction of γH2Ax and total ATM levels in irradiated lung cancer cells and tumors, indicating a sustained increased expression and activation of ATM." (PMID 28915708, 2017). "Previous studies reported higher genetic instability and lower ATM protein expression in lung cancer patients compared to controls." (PMID 28642860, 2017). "ATM, an upstream regulator of NF-κB, play a critical role in IL-6 increasing lung cancer metastasis and chemotherapeutic resistance." (PMID 27556690, 2016). "Here, we show a significant interaction between active ATM and RanBP9 in lung cancer cells at early time points following IR exposure." (PMID 26943034, 2016). "As ATM-NF-κB pathway is involved in IL-6-increased cell migration, we next explored the role of ATM-ERK/p38-NF-κB activation in TNF-α promoting lung cancer cell migration." (PMID 27556690, 2016).
lung carcinoma (continued). "Having established that ATM and MEK are synthetic lethal in lung cancer cells, we next investigated the mechanism underlying this gene–drug interaction." (PMID 27922010, 2016). "This suggests that ATM knockdown can affect the response to MEK inhibition in both the presence and absence of KRAS or BRAF mutations, both of which are common in lung cancer." (PMID 27922010, 2016). "All together, our results showed that RanBP9 is critically involved in the early steps of DDR in lung cancer cells, acting both as target and co-regulator of ATM in the effective activation of the DNA repair machinery." (PMID 26943034, 2016). "In response to IR, RanBP9 rapidly accumulates into the nucleus of lung cancer cells, but this nuclear accumulation is prevented by ATM inhibition." (PMID 26943034, 2016). "In the present study, our results reveal that IL-6 inducing ATM phosphorylation increases lung cancer metastasis via up-regulation of MMP-3/MMP-13." (PMID 26528698, 2015). "The results of our protein phosphorylation studies indicated that the presence of caffeine caused a decrease in CHK1 phosphorylation at Ser317/Ser345 but an increase in ATM phosphorylation at Ser1981 in the lung cancer cells treated with cisplatin." (PMID 25937999, 2015). "Our results suggest that the presence of caffeine increases the cisplatin-induced lung cancer cell killings by inhibiting ATR but inducing ATM activation, resulting in an increase in expression of PUMA protein and an increase in apoptosis." (PMID 25937999, 2015). "Most importantly, the in vivo test showed that the inhibition of ATM abrogate the effect of IL-6 on lung cancer metastasis via MMP-3/MMP-13 down-regulation." (PMID 26528698, 2015). "Despite IL-6 treatment increased cell retention in the lungs, the inhibition of ATM obviously abrogated IL-6's effect on lung cancer cell retention, indicating that ATM phosphorylation facilitates lung cancer cell metastasis." (PMID 26528698, 2015). "Mutations in the ATM gene have been reported in several types of cancers including familial pancreatic, breast, ovarian, colorectal, haematologic cancers and in lung cancers illustrating the significance of ATM in cancer pathogenesis." (PMID 26275218, 2015). "cAMP signaling inhibits radiation-induced ATM activation by PKA-dependent activation of PP2A, and this signaling mechanism augments radiation-induced apoptosis by reducing ATM-dependent activation of NF-κB in lung cancer cells." (PMID 24568192, 2014). "GαsQL expression also inhibited the radiation-induced phosphorylation of ATM in A594 lung cancer cells." (PMID 24568192, 2014). "This study aimed to investigate the mechanism through which cAMP signaling regulates ATM activation and cellular responses to ionizing radiation in lung cancer cells." (PMID 24568192, 2014). "Transient expression of GαsQL significantly inhibited radiation-induced ATM phosphorylation in H1299 human lung cancer cells." (PMID 24568192, 2014). "To examine the possibility that upon DNA damage Daxx is phosphorylated at an ATM consensus site(s), we expressed Flag-tagged Daxx in the human lung cancer cell line H1299 and treated these cells with the genotoxic drug etoposide." (PMID 23405218, 2013). "We aimed to evaluate, in PrCa cells, the DNA damage responsive ATM-AMPK-p21cip1 pathway we proposed earlier in lung cancer cells and found that IR indeed mediates AMPK activation downstream of ATM." (PMID 22029423, 2011).
lung carcinoma (continued). "Notably, IL-6 is also associated with chemotherapy resistance and prognosis in lung cancer patients; studies have shown that IL-6 can activate and enhance chemotherapy resistance in lung cancer by activating the ATM/NF-κB pathway." (PMID 40304000, 2025). "The most highly cited study for lung cancer related radiosensitizer publications was “Inhibition of ATM and ATR kinase activities by the radiosensitizing agent, caffeine”, published by Sarkaria JN and Abraham, RT in Cancer Research in 1999 with 946 citations to date." (PMID 40667051, 2025). "Besides, five P/LP variants (one in ATM, two in BRCA2, and two in PALB2) were also found in 1117 lung cancer patients." (PMID 37930190, 2023). "Moreover, lung cancer cells carrying ATM mutation and wild-type RAS and BRAF, such as EBC-1, display a strong dependency on MEK linked to the ATM heterozygous mutation." (PMID 35628590, 2022). "Furthermore, we present evidence that genetical or pharmacological inhibition of KDM4C overcomes radioresistance in lung cancer by inactivating the TGF-β2/Smad/ATM signaling pathway." (PMID 33558705, 2021). "Moreover, we uncover that KDM4C upregulates TGF-β2 expression by directly reducing H3K9me3 level at the TGF-β2 promoter and then activates Smad/ATM/Chk2 signaling to confer radioresistance in lung cancer." (PMID 33558705, 2021). "Similar results have been shown for AITC which induced replication stress-associated DNA damage in human lung cancer cells, where FANCD2 repair protein formed foci at stalled or collapsed replication forks, ATM/ATR, Rad18, and Chk1 were activated, and γH2A.X level was elevated." (PMID 31123866, 2020). "We asked whether ATM-deficient lung cancer cell lines are sensitive to poly-ADP ribose polymerase (PARP) inhibitors and determined the mechanism of action of olaparib in ATM-deficient A549 cells." (PMID 31481733, 2019). "Expressions of JAK1,2,、 STAT3 、PD-L1 and ATM were increased in A549CisR and H157CisR cells and could by induced by cisplatin in parental lung cancer cells." (PMID 30961670, 2019). "This is a clear indication that IL-24 modulates the ATM-mediated DDR pathway in lung cancer cells." (PMID 31783569, 2019). "Additionally, this research group indicated that miR-18a potentially increases radiosensitivity by targeting ataxia telangiectasia mutated (ATM) and hypoxia-inducible factor 1 alpha (HIF-1α) in lung cancer cells and CD133+ stem cells." (PMID 31873828, 2019). "To better understand the potential for targeting ATM-deficient lung cancer with PARP inhibitors, we studied the association between PARP inhibitor sensitivity and ATM status in 61 lung adenocarcinoma cell lines from the Genomics of Drug Sensitivity in Cancer (GDSC) project." (PMID 31481733, 2019). "To investigate whether ATM contributes to metastasis potential in cisplatin-resistant NSCLC cells, we determine the effects of ATM inhibitor on metastasis of lung cancer cells using a xenograft mouse model." (PMID 30961670, 2019).
lung carcinoma (continued). "Collectively, our findings established ATM as a potential indicator of outcome and drug responsiveness in lung cancer and inhibition of ATM may provide a novel choice in the overcome of tumor metastasis." (PMID 30961670, 2019). "Knockdown of ATM decreased expression of PD-L1 in A549cisR-siATM and H157cisR-siATM cells compare to sc cells, suggesting that ATM mediates PD-L1 expression in cisplatin-resistant lung cancer cells." (PMID 30961670, 2019). "Importantly, CP466722 treatment significantly reduced the number of metastatic tumor in the A549cisR-injected mice, suggesting that ATM play an important role in mediating tumor metastasis in cisplatin-resistant lung cancer cells." (PMID 30961670, 2019). "Overexpression of ATM contributes to cisplatin-resistance in lung cancer cells." (PMID 30961670, 2019). "The ATM rs664677 and ATM rs664143 polymorphisms were significantly associated with lung cancer susceptibility, while rs609429 was not." (PMID 29246212, 2017). "Internal validation using a bootstrap procedure with 1,000 replicated data sets confirmed the statistically significant association estimates between the ATM SNPs and lung cancer (results not shown)." (PMID 28642860, 2017). "Importantly, in vivo lung cancer metastasis test showed that ATM depletion actually reduce the number of metastatic nodules and cancer nests in lung tissues, verifying the critical role of ATM in metastasis." (PMID 27556690, 2016). "To investigate the underlying mechanism of this superior action of pterostilbene on cancer cells, we utilized a reverse-phase protein array followed by bioinformatic analysis and found that the ATM/CHK pathway is modified by pterostilbene in a lung cancer cell line." (PMID 27612029, 2016). "As a result, ATM-mutant lung cancer cells undergo apoptosis when MEK is inhibited." (PMID 27922010, 2016). "Most importantly, ATM inhibition potently repress the lung cancer metastasis in vivo." (PMID 27556690, 2016). "Thus, ATM knockdown sensitized several lung cancer cell lines with different genetic backgrounds to MEK inhibition, and even augmented the response of already sensitive BRAF mutant H1755 cells by an order of magnitude." (PMID 27922010, 2016). "Next, we addressed whether the sensitization to MEK inhibition through ATM depletion in lung cancer cell lines was paralleled by a tumour response to MEK inhibitors in vivo by using mouse xenograft models." (PMID 27922010, 2016). "ATM inhibition largely decrease TNF-α augmented lung cancer cell migration." (PMID 27556690, 2016). "Importantly, in vivo lung cancer metastasis test showed that ATM depletion actually reduce the number of metastatic nodules and cancer nests in lung tissues, verifying the critical role of ATM in lung cancer metastasis." (PMID 27556690, 2016). "Our previous studies showed that MMP-13 mediate IL-6 increasing lung cancer metastasis via ATM activation, therefore, we speculate that MMP-13 might be a critical potential target for TNF-α augmenting lung cancer migration." (PMID 27556690, 2016). "Our previous studies show that the phosphorylation of ataxia-telangiectasia mutated (ATM) induced by interleukin 6 (IL-6) treatment contributes to multidrug resistance formation in lung cancer cells, but the exact role of ATM activation in IL-6 increased metastasis is still elusive." (PMID 26528698, 2015). "The effect of IL-6 on ATM raises the question of whether ATM activation is involved in IL-6 correlated lung cancer metastasis." (PMID 26528698, 2015).
lung carcinoma (continued). "Therefore, it would be important to further determine the role of the ATM and DNA-PK kinases in how caffeine potentiates these lung cancer cells to cisplatin treatment in future studies." (PMID 25937999, 2015). "The mechanism through which the presence of caffeine causes a greater increase of ATM activation in the cisplatin-treated HTB182 and CRL5985 lung cancer cells is unknown." (PMID 25937999, 2015). "All of these results suggest that the presence of caffeine potentiates both HTB182 and CRL5985 lung cancer cells to cisplatin treatment by inhibiting ATR activity but inducing ATM activation, resulting in an increase in expression of the PUMA protein and an increase in apoptosis." (PMID 25937999, 2015). "While the functional significance of the ATM mutations identified has not been determined, ATM polymorphisms are known to affect lung cancer risk." (PMID 26438152, 2015). "ATM mutations and FANCF promoter-methylation are reported in lung carcinomas." (PMID 26438152, 2015). "Here we sought to elucidate whether the ATM, FA and ATR pathways interact with each other and whether the ATM, FA and ATR pathways may be new diagnostic and therapeutic biomarkers for lung cancer." (PMID 26438152, 2015). "Despite the effects of IL-6 in ATM phosphorylation and in tumor invasion were documented respectively, the exact role of ATM phosphorylation in IL-6 increasing lung cancer metastasis is still unknown." (PMID 26528698, 2015). "As EMT could be affected by the composition and structure of ECM, the findings that ATM phosphorylation increases MMP-3/MMP-13 expression and promotes lung cancer metastasis indicate that the phosphorylation of ATM might be involved in IL-6 promoting EMT." (PMID 26528698, 2015). "In order to have a better control of confounding of gender or smoking, we performed a case-control study to identify the association between the polymorphism of ATM rs189037 and the risk of lung cancer in the non-smoking females in Chinese Han population." (PMID 24819391, 2014). "We respectively studied associations between ATM rs189037 and lung cancer risk in non-smokers and smokers." (PMID 25541996, 2014). "Distribution of ATM rs189037 genotypes and ORs for lung cancer cases and controls." (PMID 24819391, 2014). "Moreover, inhibition of radiation-induced ATM phosphorylation by the cAMP signaling system was observed in human lung cancer cells, murine melanoma cells, and murine lung tissue, suggesting that the inhibition occurs in many tissues." (PMID 24568192, 2014). "In post-thawed lung cancer stem cells, the majority of pathways showing significant alteration in gene expression are the pathways involved in cell cycle, mitosis, and ATM that also regulates a number of pathways involved in DNA repair, cell cycle, and apoptosis." (PMID 22592563, 2013). "Heterozygous NBS1 splicing mutation (IVS11+2insT) detected in sporadic gastric, colorectal and lung cancers led to defects in crucial binding to Mre11, Mdc1 and BRCA1, and caused impaired ATM phosphorylation in response to low-dose irradiation in the heterozygous state." (PMID 24349281, 2013). "PARP1 Inhibition has also been shown to be selectively toxic to ATM-defective tumor cell lines in vitro and to increase radiosensitivity of other ATM-proficient cell lines, including nonsmall-cell lung cancer, medulloblastoma, ependymoma, and high-grade gliomas." (PMID 22693661, 2012). "This includes hypermethylation-mediated silencing of mutL homolog 1 (MLH1), ataxia-telangiectasia mutated (ATM), and O-6-methylguanine-DNA methyltransferase (MGMT), which compromises DNA damage response and contributes to chemo-resistance characteristic of dormant lung cancer cells." (PMID 41303477, 2025).